VIP (vasoactive intestinal peptide)
Diseases named in the same sentence as VIP in open-access papers (continued):
Sharing a sentence is not in itself a finding about the gene and the disease.
tumor (continued). "The tumor tissues were stained for VIP, CD8 and DAPI, while the splenocytes were analyzed via flow cytometry for levels of CD3, CD4+, CD8+, CD4+PD1+ and CD8+PD1+ T cells." (PMID 30400835, 2018). "Tumor cells have also capacity to produce a large variety of neuropeptides like vasoactive intestinal peptide (VIP), bombesin, substance P, and so on." (PMID 28760150, 2017). "To characterize the role of these peptides in hypoxic areas of GBM, we have analyzedthe expression of PACAP or VIP precursor proteins in U87MG tumor cells, grown for 24h under normoxia or hypoxia." (PMID 27303300, 2016). "It is therefore very tempting to suggest the use of growth-inhibiting VIP/PACAP analogues for the treatment of human tumours." (PMID 25504760, 2015). "VPAC2 visualisation with this simple and rapid immunohistochemical method will facilitate identification of candidate tumours for vasoactive intestinal peptide (VIP)-based diagnostics or therapeutic interventions." (PMID 25504760, 2015). "Whereas growth-promoting activities have been reported for VIP, growth-inhibiting properties have been found for VIP antagonists in various tumour models." (PMID 25504760, 2015). "Other interesting afferent crosstalk pairs involved LRP8 receptor in tumor activated by a double stimulus of RELN and CLU proteins secreted by adjacent mucosa, and VIP, an intestinal peptide that causes vasodilatation, linked to MME receptor in tumor cells." (PMID 24597571, 2014). "Almost all tumor cells (100%) were strongly positive for synaptophysin and CgA, and 40% of cells strongly positive for VIP." (PMID 25081061, 2014). "Since Virgolin initially reported use of 123I labeled VIP in the imaging study of tumor VIP receptors, several potential 123I, 99 mTc, F-18, and 64Cu labeled VIP analogues have been developed." (PMID 24459669, 2013). "While these isotope-labeled VIP analogues demonstrated good tumor receptor specificity, a common problem is the poor in vivo stability of VIP polypeptide, which leads to low uptake by tumor tissues and a depressed signal-to-noise (S/N) ratio." (PMID 24459669, 2013). "However, watery diarrhea may be caused by the composite tumor through secreting VIP." (PMID 23587063, 2013). "Radiolabeled analogs of somatostatin, bombesin or vasoactive intestinal peptide (VIP) are now increasingly used for tumor imaging and therapy." (PMID 22824624, 2012). "One patient had findings consistent with VIP-oma (vasoactive intestinal polypeptide secreting tumor)." (PMID 15691381, 2005). "In addition, sample P4, identified as a tumor secreting vasoactive intestinal peptide (VIP) based on biobank data, showed a substantial increase in VIP mRNA expression." (PMID 40217502, 2025). "In addition, immune activities, especially those within LNs and those associated with a tumor context, are regulated by neurotransmitters including NMU, CGRP, VIP, SP, and NE." (PMID 41030446, 2025). "Regardless, surgery to remove the VIP-producing tumor is the definitive form of treatment." (PMID 39328672, 2024). "Serum VIP production in neuroblastic tumors seems to occur during tumor differentiation." (PMID 39328672, 2024). "Furthermore, VIP antagonist alone or in combination with anti-PD-1 antibody significantly reduced tumor size in CT26 tumor-bearing SCID mice, at least in part, via an increase in M1/M2 macrophage ratio and TAM phagocytic function." (PMID 36650220, 2023). "In SCID mice, VIP antagonist alone significantly reduced tumor growth." (PMID 36650220, 2023). "Interestingly, the combination of VIP antagonist and anti-PD-1 antibody significantly reduced tumor volume compared with the control and tended to further attenuate tumor growth compared with the VIP antagonist or anti-PD-1 antibody alone." (PMID 36650220, 2023). "In addition, VIP is released from tumor and immune cells, and it regulates immune reactions such as anti-inflammatory activities through interactions with VIPR1 and VIPR2." (PMID 37405999, 2023).
tumor (continued). "VIP expression has been shown to correlate with advanced tumor stage in colorectal carcinoma." (PMID 36650220, 2023). "In immunodeficient SCID mice lacking T and B cells, VIP antagonist alone or in combination with anti-PD-1 reduced CT26 tumor growth, which was associated with increases in M1/M2 macrophage ratio and macrophage phagocytosis of CT26 in the tumors." (PMID 36650220, 2023). "We speculate that tumor-secreted VIP might affect tumor progression by interacting with tumor-infiltrating pDCs, a possibility warranting further investigation." (PMID 37817484, 2023). "Our findings indicate that in gastrointestinal malignancies, further in vitro and in vivo validation is necessary to elucidate the mechanism of interaction between VIP and ZEB1 and to determine how VIP supports ZEB1-mediated EMT involved in tumor invasion and metastasis." (PMID 37444395, 2023). "Furthermore, activation of VPAC1 by VIP stimulates the expression of angiogenic VEGF, the pro-inflammatory enzyme COX-2, and the increased activity of MMP-2 and 9 in tumours derived from VIP-treated PC3 cells." (PMID 35011543, 2022). "The expressions of CCR1, PNOC, and VIP genes were significantly correlated with tumor purity, B cell infiltration, CD8+T cell infiltration, CD4+T cell infiltration, macrophage infiltration, neutrophil infiltration and dendritic cell infiltration, and the differences were statistically significant." (PMID 35174205, 2022). "Our results with selective depletion of CD4+ or CD8+ T cells and the generation of cancer-antigen specific immunological memory suggest that the dominant effect of VIP-R antagonists is via inhibition of paracrine signaling of VIP produced by tumor cells on T cells that express the VIP-R." (PMID 36302761, 2022). "In the case that the patient would have gained initial symptom control, the recommended next treatment step should be the application of a long-acting somatostatin analogue, such as octreotide or lanreotide, which blocks the release of VIP from tumor tissue and improves symptoms." (PMID 33398457, 2021). "Furthermore, VIP-conjugated nanoparticles have been developed to deliver the cytotoxic drug to tumor cells overexpressing VPAC114." (PMID 31559013, 2019). "We hypothesize that VIP expression by cancers represents a targetable pathway for immune escape, and that antagonists of VIP signaling would induce an anti-tumor response when used alone or in combination with other immune checkpoint inhibitors." (PMID 30400835, 2018). "Although neuropeptides such as vasoactive intestinal peptide (VIP) can promote tumor growth and activate antiapoptotic signaling in differentiated cancer cells, it is not known whether they can activate antiapoptotic mechanisms in CSCs." (PMID 28569785, 2017). "Therefore, in the present study, we evaluated the effect of PACAPand VIP on tumor cell infiltration grown in a hypoxic microenvironment." (PMID 27303300, 2016). "The rapid immunocytochemical VPAC2 receptor visualisation using SP235 may also be helpful to identify candidate tumours for VIP-based diagnostics or therapeutic interventions." (PMID 25504760, 2015). "The VIP positive cells were clustered and scattered among the tumor cells." (PMID 25081061, 2014). "Tumor 6 had high levels of VIP and came from a patient with the clinical syndrome of VIP-oma." (PMID 15691381, 2005). "Additionally, mRNA analysis confirmed the VIP-secreting tumor diagnosis for patient P4 and suggested that patients P3 and P6 may have a rare form of PanNET, glucagonoma." (PMID 40217502, 2025). "PD-1 tended to increase in TAMs isolated from VIP antagonist-treated mice, and therefore we hypothesized that the combined treatment of VIP antagonist and anti-PD-1 antibody may have an additional effect on reducing tumor growth and enhancing macrophage function." (PMID 36650220, 2023). "However, VIP/VIPR1 signaling has also been reported to inhibit tumor growth/proliferation." (PMID 35864952, 2022).
tumor (continued). "To investigate whether VIP can elicit anti-tumor effects in vivo, we established HCC xenograft mouse models by subcutaneously implanting VIPR1 overexpressing HCCLM3 cells (HCCLM3-VIPR1) or vector transduced with HCCLM3 cells (HCCLM3-Vector) in the back of nude mice." (PMID 35864952, 2022). "Thus, to test the autocrine effect of VIP made by tumor cells on VIP- receptor expressing tumor cells, we first evaluated whether inhibiting VIP-R signaling affects the growth of PDAC cells in vitro." (PMID 36302761, 2022). "Next, we determined whether treatment with VIP regulated tumor distant metastasis." (PMID 35864952, 2022). "A different signalling pathway is triggered by the vasoactive intestinal peptide (VIP), a modulator of inflammatory responses, whose receptors, VPAC1 and VPAC2, are overexpressed in many cancer cells including HCC, probably due to the inflammatory state associated with the development of tumours." (PMID 31775395, 2019). "This suggests that VIP/PACAP may affect tumor growth and differentiation." (PMID 31559013, 2019). "In addition to targeting the VIP-induced signaling pathways to minimize the drug resistance, cytotoxic drugs conjugated to VIP could be more effectively targeted to the tumor sites and eliminate both CSCs and DC." (PMID 28569785, 2017). "Therefore, we have analyzed the effect of 100nM PACAP and VIP on tumoral cells invasivity." (PMID 27303300, 2016). "VPAC1, the receptor for vasoactive intestinal peptide (VIP), is overexpressed in PCa and contributes to tumor proliferation and progression." (PMID 41251982, 2025). "Beyond structural invasion, infiltrated nerves actively enhance tumor malignancy by releasing neurotransmitters and neuropeptides, such as NE, acetylcholine, SP, CGRP, and vasoactive intestinal peptide (VIP)." (PMID 41009819, 2025). "VIP antagonists inhibit c-fos mRNA induction by VIP and retard the growth of CAPAN-2 cells in nude mice indicating that VIP receptor antagonists have a tumor-intrinsic cytostatic effect." (PMID 36302761, 2022). "In gene expression studies of SRC transformed by several cells, the genes IL8/CEF4, VIP, HMOX1, PLCPI, and UPP1 were identified as signature SRC aggressive tumor genes." (PMID 28945796, 2017). "Thisview is also corroborated by the high expression of PACAP, VIP, VIPRs, HIFs, and EGFR inthe frozen tumor sample." (PMID 27303300, 2016). "PanNETs represent a heterogeneous group of tumours, presenting either as hormonally active tumours (producing gastrin, insulin, glucagon, somatostatin, vasoactive intestinal peptide or growth hormone-releasing hormone) or as non-functioning tumours." (PMID 39949334, 2025). "On the other hand, the expression of VIP varied among different tumor histologies, with several histologies showing no detectable protein expression." (PMID 37444395, 2023). "The analysis of tumor-infiltrating leukocytes demonstrated that VIP antagonist did not significantly change the population of macrophages, M1 and M2 macrophages, as well as NK cells in the implanted tumors compared with the controls." (PMID 36650220, 2023). "Unfortunately, this was not confirmed by biochemically measuring the secretion of VIP from the tumor, because the assay is currently unavailable in mainland China." (PMID 25081061, 2014). "VIP/VIPR1 signaling maintained tumor proliferation and invasiveness by upregulating the expression of cyclins and angiogenic factors, including cyclin D1, MMP-2/MMP-9, VEGF, and COX-2, as well as stimulating tumor growth through the activation of PKA/ERK1/2 pathway." (PMID 35864952, 2022).
tumor (continued). "For example, the addition of VIP to lung cancer cells elevated cAMP levels, leading to the activation of transcription factors promoting expression of nuclear oncogenes and growth factors along with a rise in VEGF secretion and tumor angiogenesis through the cAMP/PKA and PI3K signalling pathways." (PMID 35203615, 2022). "VIP can function via cAMP/PKA in non-tumour cells as well as cAMP/EPAC/ERK/PI3K in tumour cells." (PMID 35011543, 2022). "The vasoactive intestinal peptide (VIP) family of neuropeptides and their receptors, referred in this article as the “VIP-receptor system”, has been reported to regulate proliferation, differentiation, and migration in a number of tumor cell types and more particularly in GBM cells." (PMID 30669581, 2019). "It has recently been shown that the multipotent tyrosine kinase inhibitor sunitinib may exert a particular effect in VIP-secreting panNENs irrespective of its effect on tumor growth." (PMID 29349087, 2017). "Despite being the recommended medication, VIP-secreting pheochromocytomas had a relatively poor response to octreotide, a finding consistent with previous reports, thus implying the lack of somatostatin receptors in these VIP-containing tumor cells." (PMID 25081061, 2014). "Moreover, we hypothesized that this novel peptide would exhibit enhanced tumor-targeted characteristics and generate a better image when used in molecular imaging because it selectively binds to one subtype of VIPR with a higher affinity than VIP." (PMID 23365656, 2013). "SLC28A2, VIP, CMKLR1, MARCO, and NOD2 were detected at low levels in non-tumor and tumor cells." (PMID 38742117, 2024). "This cell line expressed both neuroendocrine markers and estrogen receptors, and these cells were morphologically representative of the original tumor; however, staining for many common NET antigens, including somatostatin receptors and VIP, was negative in the original culture." (PMID 39649120, 2024).
cancer (46 papers, 2009 to 2026). A tumor composed of atypical neoplastic, often pleomorphic cells that invade other tissues. "VIP expression from TCGA PANCAN tissue samples was analyzed against the expression levels of 760 cancer-associated genes." (PMID 37444395, 2023). "The VIP sequence is highly conserved across mammals and rarely mutated in cancers, in support of a critical role for VIP-signaling in normal physiology." (PMID 37444395, 2023). "Some of these genes, such as MAPK, NOS2, CDK2, and TIMELESS, have been previously associated with VIP in non-cancer models." (PMID 37444395, 2023). "The increase in VIP/PACAP-mediated signalling due to overexpression of their receptors represents a standard hallmark in different cancers." (PMID 35203615, 2022). "Vasoactive Intestinal Peptide, encoded by VIP, is known to be involved in autocrine as well as paracrine signaling loop that promotes cancer growth in multiple cancer types." (PMID 34439877, 2021). "We performed hypothesis-generating in silico analyses of associations of autocrine VIP gene expression with gene targets and pathways in cancer." (PMID 37444395, 2023). "In particular, the extension of our investigation to datasets such as COSMIC, in which somatic cancer mutations are collected, could certainly help to get more insights into the role of the vIP in the mutation processes." (PMID 31307386, 2019). "In other words, whether the known VIP variants are relevant to only somatic samples (that are thought to be uninvolved in a cancer), only cancer tissue samples, or both." (PMID 31394823, 2019). "We hypothesized that VIP expression may promote cancer-associated signaling pathways." (PMID 37444395, 2023). "Vasoactive intestinal peptide (VIP) is a neuropeptide involved in cancer proliferation and immune suppression." (PMID 41478571, 2025). "Overall, VIP is known to be a potent neurotransmitter further involved in the regulation of circadian rhythms, hormones, the intestines and cancer." (PMID 37106696, 2023). "VIP (vasoactive intestinal peptide) is a 28-amino acid peptide hormone expressed by cancer and the healthy nervous system, digestive tract, cardiovascular, and immune cell tissues." (PMID 37444395, 2023). "The downstream signaling mechanisms and importance of the autocrine secretion of the vasoactive intestinal peptide (VIP) in cancer remains poorly understood." (PMID 37444395, 2023). "VIP is also known to exert paracrine effects in cancer by supporting the immunosuppressive activity of CD4+CD25+ regulatory T cells and tolerogenic dendritic cells." (PMID 37444395, 2023). "In this exploratory analysis, we utilized an in silico gene expression model to uncover new downstream signaling pathways of VIP in cancer and corroborate these pathways in analyses of healthy tissues." (PMID 37444395, 2023). "Determining the downstream effects of VIP in cancer is crucial to understanding its role as a circulating biomarker and VPAC as a diagnostic, prognostic, or predictive target." (PMID 37444395, 2023). "Given the known importance of VIP in embryogenesis, we also sub-grouped individual cancer histologies by germ layer of origin and looked for germ layer-specific expression associations." (PMID 37444395, 2023). "To comprehensively characterize the signaling landscape of autocrine VIP in cancer, we conducted an in silico gene expression analysis." (PMID 37444395, 2023). "To date, the primary function of autocrine VIP signaling was thought to drive cancer cell proliferation." (PMID 37444395, 2023). "The importance of autocrine VIP as a biomarker or therapeutic target in cancer has remained elusive for many years." (PMID 37444395, 2023). "The divergent findings in VIP and ZEB1 expression associations between tissues (healthy and malignant) and cancer cell lines highlight the need for future studies in both settings." (PMID 37444395, 2023).